CD4 (CD4 molecule)
Diseases named in the same sentence as CD4 in open-access papers (continued):
Sharing a sentence is not in itself a finding about the gene and the disease.
infection (continued). "Because salivary nucleosides potentiated IL-10 production and mediated susceptibility to the infection, we addressed whether the CD4+CD25-expressing Treg markers in the CD4+CD25-population could contribute to nucleoside-induced IL-10 production." (PMID 25849562, 2015). "We show that TBEV-specific CD4+ T cells induced after vaccination and infection are polyfunctional Th1 cells, but the cytokine patterns after vaccination are different from those after natural infection." (PMID 26465323, 2015). "Moreover, RELM-β has been shown to modulate host defense during helminth parasite infections (Trichuris muris, Nippostrongylus brasiliensis), by impacting on parasite viability and on CD4+ T cell cytokine responses during infection." (PMID 26285214, 2015). "This trans-infection process greatly increases the efficiency of CD4+ T-cell infection." (PMID 25809903, 2015). "Fast infection of CD4+ T cells can explain the CD4+ T cell and viral load dynamics in the early stages, while slow infection of macrophages may explain the dynamics in the advanced stages of infection." (PMID 26709961, 2015). "Similarly, in healthy individuals, the initial immune response in the lung involves fungal recognition by innate immune cells and subsequent expansion of Cryptococcus-specific CD4+ T cells to control the infection." (PMID 25492918, 2015). "Latent infection of γδ cells could occur at other times as well, when cellular activation results in upregulation of CD4 expression." (PMID 26473478, 2015). "Several studies have shown that both CD4+ and CD8+ T-cell responses play important roles in controlling HCV replication during infection, and certain HLA alleles have been significantly associated with differential infection outcome." (PMID 26579127, 2015). "Furthermore, GATA-3-expressing CD4+ T cells started to decrease after 28 days post-infection, but their levels were maintained in the lungs of mice infected with both virulent Mtb K and H37Rv (upper-right panel)." (PMID 26675186, 2015). "Moreover, overnight treatment of HIV+ FDC with sCD21-Ig prior to addition of healthy, activated CD4 T cells blocked viral transmission and disrupted infection." (PMID 26623655, 2015). "CD4+ T cells from LPL were the most permissive (63%) to infection." (PMID 26034905, 2015). "CD8 T cells and CD4 T cells expanded approximately five-fold by day 6 post infection." (PMID 26070118, 2015). "The B cell-mediated amplification of IFN-γ production by CD4+ memory T cells in response to ex vivo antigen recall described here, may occur in vivo and at the site of infection, too." (PMID 26379242, 2015). "This may explain why increases in PPS-specific B cell numbers do not correspond with antibody levels or OPT in individuals with CD4<200 as a result of long term infection with chronic inflammation." (PMID 25908995, 2015). "Hence, we find that the intuition that treatment will favour the low virulence viruses is true in the long run (at equilibrium) in the case where the proportion of low CD4 transmissions (Bi/Ai) is greater for high SPVL infections." (PMID 26609066, 2015). "We have highlighted only these two distinct cell fates using our system; however, there is ostensibly a whole “spectrum” of possible CD4+ T cell responses to recognition of cognate antigen during infection, adding necessary diversity to the immune system’s response to pathogens." (PMID 26697015, 2015). "These global changes, if replicated following infection with SIVmacC8, could create a situation where uninfected CD4+ lymphocytes are refractory to infection with a newly introduced SIV strain." (PMID 25834093, 2015). "This disjunction between direct productive infection and depletion highlights the need for future studies to elucidate the mechanisms that account for CD4+ T cell depletion in the lungs and maintenance of macrophage populations even in the setting of direct infection." (PMID 25933119, 2015).
infection (continued). "Therefore, repeated infection with schistosome larvae leads to a significant increase in the proportion of apoptotic and dead CD4+ cells, which would affect the overall number of cells that can divide and secrete cytokines." (PMID 25624353, 2015). "We also use HIV Duo-Fluo I to explore the theories of how HIV latency is established; namely, whether it occurs through infection of activated CD4+ T cells that return to a resting state or through the direct infection of resting CD4+ T cells." (PMID 26067822, 2015). "Second, using HIV-1 particles whose envelope glycoprotein was replaced by the one from vesicular stomatitis virus, which enables infection in a CD4- and coreceptor-independent manner, we proved that CXCL12/SDF-1 failed to inhibit the viral replication (occurring after viral entry)." (PMID 26097474, 2015). "Latent infection of resting CD4+ T-cells therefore represents the major barrier to HIV-1." (PMID 26362311, 2015). "Some of that difference may be attributable to increases in sub-clinical infection and inflammation present among women with lower CD4+ counts." (PMID 25849627, 2015). "Most of the IFNγ is produced by CD4+ T-cells at later stages of the infection." (PMID 26296209, 2015). "Thus, the CD4+ T-cell count change evaluation of these species were included in all types parasite infection category." (PMID 26415705, 2015). "However, at week 6, the group given Treg cells displayed a more intense recruitment of macrophages and granulocytes to the site of infection than the group receiving the combination of CD4+Foxp3- T cells and Treg cells." (PMID 26512987, 2015). "Here we show how IFN infection by infected CD4+ T cells is directly modulated by HIV infection." (PMID 26375588, 2015). "Instead, only CD4+ Foxp3− IL-4+ Th2 cells showed increased IL-10 production upon infection." (PMID 26195548, 2015). "Absolute CD4+ T cell counts are affected by variables such as age, season, ethnic origin, the time of day the sample was taken, exercise, smoking and inter-current infection." (PMID 26110761, 2015). "In parallel, we analyzed CD4+ T cells for FLUAVsw infection-related changes in Ki-67 expression." (PMID 25971313, 2015). "Interestingly, mouse CD8 T cells are more promiscuous in the expression of tissue homing molecules than CD4 T cells with the latter homing specifically to the original site of infection, while CD8 T cells have a more wide spread tissue distribution." (PMID 26441961, 2015). "CD4 cells, also known as helper T- cells (Th1/Th2) help fight infection by producing cytokines such as IFN-g (Th1) that generally promote cell-mediated immunity or IL-4 (Th2) which fights infection by triggering humoral immune responses through antibody production." (PMID 26371878, 2015). "Additional experiments are required to demonstrate whether CD8+ T cell maintenance after vaccination/infection may be reliant on signal from CD4+ T cells." (PMID 26619062, 2015). "Thus, spread of infection from MDM to primary CD4+ T lymphocytes required productive HIV-1 replication in MDM under the conditions of our assay." (PMID 26186441, 2015). "The neurotropic, neurovirulent SIVmac17E-Fr strain initially characterized extensively in macaque models of HIV has been demonstrated to lead to infiltration in the brain, where infection of microglial/macrophage-related cells represents a reservoir for the virus in a CD4-independent manner." (PMID 25834093, 2015). "The loss of thymocytes during X4-tropic LAI infection would not allow buffering the CD4+ T cell levels in tissues resulting in dramatic depletion of these cells." (PMID 26169178, 2015). "Additionally, in vivo, most HIV-infected resting CD4+ T cells exhibit a memory phenotype, suggesting that they arose from the infection of previously activated CD4+ T cells." (PMID 26067822, 2015).
infection (continued). "Chronic SHIVAD8 infection results in persistent innate activation and fluctuations in the type and number of CD4+ T cells, which may be critical for the induction of cross-reactive serum neutralization." (PMID 25858157, 2015). "Thus, the findings suggest a mechanism by which infectious virus can be retained within a neutral pH compartment inside the cell but periodically cycled to the cell surface for infection of CD4 T cells." (PMID 26623655, 2015). "Because of the essential effects of Smad4 in the control proper CD4+ T-cell differentiation, consequently changes in CD4+ T cell help or Treg function could alter the course of infection." (PMID 26583325, 2015). "Thus, both, invasive infection and exposure to high antigen concentrations are able to induce rapid maturation of neonatal CD4+ T cells." (PMID 26195040, 2015). "Furthermore, formation of DC–T cell conjugates results in polarized release of captured virus particles towards T cells for establishment of optimal CD4+ T cell infection." (PMID 25760631, 2015). "Furthermore, all patients who recovered had virus-specific CD8+/CD4+ (IFN-γ+CD8+ >400 per million PBMC and/or IFN-γ+CD4+ 800 per million PBMC) at least at one time point after infection." (PMID 25967273, 2015). "CD4-positive T cells also have a role in preventing infection, but whether these cells act as direct effectors or indirectly through modulation of antibody responses is unclear." (PMID 26342424, 2015). "Similarly, IFNγ production by HSV2 specific memory CD4 T cells in the vaginal cavity leads to a local chemokine response that attracts viral specific CD8 T cells that subsequently control a challenge infection." (PMID 26441961, 2015). "It was found that the percentage of splenic CD4(+) and CD11c(+) cells in semi-immune mice on day 7 post-infection was significantly higher than in infected naïve counterparts, suggesting a potentially protective cooperation of CD4(+) and CD11c(+) cells against Plasmodium infection." (PMID 25626734, 2015). "In line with our primary hypothesis, prospective data from 499 HIV-1 SCs did suggest that CD4:CD8 ratio in early (primary) infection has three main features." (PMID 26191056, 2015). "Hence, we decided to further investigate the potential relationship between the counts/percentages of B cells at the time of initial infection, and CD4+ T-cell counts/viral loads at the baseline visit plus the 12-month follow-up visit." (PMID 26436092, 2015). "In addition, the absence of detectable virus in the supernatant of infected cell cultures after the infection period (see Results section) invalidates the possibility of APOBEC carryover by PBMC or purified T CD4 positive cell-derived viruses." (PMID 26413773, 2015). "We also monitored CD4+ T cells in blood post JRCSF inoculation over the course of infection." (PMID 26169178, 2015). "These latent reservoirs established during early infection have long life span, include resting CD4+ T cells, macrophages, central nervous system (CNS) resident macrophage/microglia, and gut-associated lymphoid tissue/macrophages, and can actively produce virus upon interruption of the cART." (PMID 26405463, 2015). "The method to detect these “dysfunctional” antigen-specific CD4+ T cells in blood and at the site of infection, provides a new opportunity to pursue this important question experimentally and to understand the overall mechanisms that lead to chronic HCV infection." (PMID 25767470, 2015). "At this late stage of infection it was up-regulated in activated CD4+ T cells of both wt (mean = 67.9-fold) and Tnf-/- (mean = 48.6-fold) mice to a similar extent, although expression of IL-17A was generally low and barely detectable either by real-time PCR or by intracellular cytokine staining." (PMID 26834705, 2015).
infection (continued). "In summary, this study suggests that immunisation with Tat-fused TPI may contribute to enhance CD4+ T-cell response and decrease hepatic egg granulomatous area after S. japonicum infection, but the anti-infection efficiency was limited." (PMID 26714844, 2015). "Reports show that shortly after infection, CD4+ T cell and CD8+ T cell levels declined." (PMID 26179610, 2015). "We wished to determine if the Vif-dependent restrictions observed in the APOBEC3 over-expression assays could be recapitulated in infections of primary chimpanzee CD4+ T cells." (PMID 26394054, 2015). "Our results demonstrated the early infection of both Tfh and effector memory CD4 T cell subsets." (PMID 26640894, 2015). "Moreover, in our hospital, 20% of patients newly diagnosed with HIV infection have a CD4+ count < 200 and are likely to receive antibiotics to cure or prevent infection (S. De Wit, personal communication)." (PMID 26691198, 2015). "Moreover, SIV replication in CD4+ T cells peaks around 2 weeks post infection in secondary lymphatic tissues and gut mucosae, whereas virus replication in lung macrophages was very limited in this time frame (Fig 1A1–1A2), consistent with a previous report." (PMID 25933119, 2015). "Importantly, this strain acted as a vaccine and was able to protect CD4+ T-cells depleted and immunocompetent mice against subsequent infections with lethal doses of C. neoformans or C. gattii." (PMID 26322039, 2015). "Since PGE2 inhibits production of IFN-γ by CD4+ T-cells via direct and indirect ways, it is possible that the locally-concentrated PGE2 of parasite at the site of infection could influence the function of immigrating CD4+ T-cells." (PMID 26466097, 2015). "We then compared PDR in individuals with >500 CD4 T cells/μL vs. <350 CD4 T cells/μL as the first group would be expected to be enriched in individuals at early chronic stage, while the later group in individuals with advanced infection." (PMID 26558396, 2015). "Infection of untreated PBMCs resulted in a 3.5-fold decrease in productive infection as compared to untreated CD4+ T cells from the blood, while infection of untreated HLACs from tonsil resulted in a 4-fold decrease in productive infection as compared to untreated CD4+ T cells from the same tissue." (PMID 26067822, 2015). "Among the 120 PHI subjects, we observed that those subjects whose viral set points were above or equal to 4.5 lg copies/mL had persistently lower CD4+ T-cell counts and higher viral loads throughout the course of their infection compared to those whose viral set points were below 4.5 lg copies/mL." (PMID 26436092, 2015). "Similarly, SP-A prevents HIV-1 cis-infection of CD4+ T-cells, yet enhances cis-infection of DCs and trans-infection of T-cells." (PMID 25642836, 2015). "In HIV, CD4+ T cells are best known as the primary targets of infection." (PMID 26302050, 2015). "Therefore, although the interval from infection until the CD4 cell count reached <350 cells/μL is longer than what we report here, a direct comparison between the previous report and ours is not possible." (PMID 26000028, 2015). "Interestingly, double infection occurred preferentially in central memory CD4+ T cells compared to naïve CD4+ T cells." (PMID 26559763, 2015). "Static cultures of Jurkat cells, an HIV-1-susceptible human CD4+ T-cell line, allow HIV-1 to propagate both by the cell-free and cell-to-cell infection, while under shaking conditions, Jurkat cells allows HIV-1 to replicate only by the cell-free infection." (PMID 26441404, 2015). "By day six post infection CD4 and CD8 T cells get activated and accumulate in liver in spleen." (PMID 26070118, 2015). "Thus, the possibility that IL-10 secreted by CD4+ T cells during infection is responsible of MHC class II decrease on DCs cannot be ruled out." (PMID 26720149, 2015). "Similarly, in a mouse model of OPC, CD4+ Th17 cells are generated in mice following a re-challenge infection." (PMID 25849644, 2015).
infection (continued). "Similarly, the infection of C3HeB/FeJ mice (H-2k genetic background) with LM induces a dominant CD4+ T cell response directed to the LLO 215–234 peptide." (PMID 25874208, 2015). "Accordingly, preventing release of CD4+ exosomes at the site of the HIV-1 virological synapse could facilitate infection of the target cell." (PMID 25423108, 2014). "We speculate that IL-17 and/or IFN-γ producing CD4+ T cells may help to clear the infection in infants and children, but additional studies are needed to address this hypothesis and to determine why the infection is not cleared in all children." (PMID 24714675, 2014). "We also observed that some follicle-associated CD4 T cells expressed PD-1 but not CxCR5, particularly by one month after infection in the spleen, and at the chronic phase in lymph nodes." (PMID 24763747, 2014). "It has also been suggested that evolution of highly macrophage-competent strains of SIV appears late in the course of disease and monkeys that survive the acute course of a severely CD4-depleting strain of SHIV exhibit almost exclusive infection of macrophages in lymphoid tissues many months later." (PMID 24465411, 2014). "The ability of HIV-1 to change its tropism by acquiring glycoproteins from other viruses or endogenous retroviruses could also explain published reports of infection of non-CD4+ cells in vivo, including epithelial cells and hepatocytes." (PMID 25010677, 2014). "If productive HIV infection in macrophages occurred by surface fusion, enhancing plasma membrane fusion by tethering CD4 to the cell surface through LCK expression should have resulted in increased infection efficiency during all stages of the HIV-1 entry pathway." (PMID 24465876, 2014). "To check whether this expansion was analogous in M. bovis BCG infection, we first analysed the expression of FoxP3 in the CD4+ T cell population during the course of infection." (PMID 25050936, 2014). "HCMV-specific CD4+ T-cells showed a sensitivity of 100% and a specificity of 73% in detecting group 4 patients with severe infections, whereas total CD4+ T-cells (with an optimal cut-off of 350 cells/μL) showed a sensitivity of 89% and the same 73% specificity." (PMID 25166270, 2014). "Analysis of CD4+ T-cell populations shows that upon activation of naïve CD4+ T-cells (a population relatively refractory to infection) the expression levels of RUNX1, RUNX3 and CBF-β drop (correlating with greater susceptibility to infection)." (PMID 24651404, 2014). "The data we present here showing both elevated IL-10 expression in infected (versus virally exposed or naïve) CD8αneg DCs together with the finding that these cells are able to induce IL-10 expression in naïve CD4 T cells likely explains how infection of CD8αneg DCs contributes to total IL-10." (PMID 24613988, 2014). "However, mice that received C57Bl6 CD4 T cells exhibited a robust germinal center response following MHV68 infection." (PMID 24789087, 2014). "Furthermore, we validated these results by applying RT-qPCR to the analysis of gene expression pattern of HIV-1 infected and mock-infected primary CD4+ T cells at day 3 post-infection." (PMID 25462981, 2014). "Finally, the reporter assay from HIV-1 integrants provided further evidence that CD4 localization to lipid rafts is required for productive infection." (PMID 24465876, 2014). "The gut is the major site of HIV-1 replication and the gut mucosal homing receptor α4β7-integrin binds HIV-1 Env with high affinity and might be important for productive infection of CD4+ T cells." (PMID 24558379, 2014). "These different strategies may explain the different outcome of infection by these different subgroups of gammaherpesviruses in the context of defective germinal center responses that result from defective CD4 T cell help." (PMID 24789087, 2014).